TMEM43 (transmembrane protein 43)
Diseases named in the same sentence as TMEM43 in open-access papers (continued):
Sharing a sentence is not in itself a finding about the gene and the disease.
cancer (21 papers, 2010 to 2025). A tumor composed of atypical neoplastic, often pleomorphic cells that invade other tissues. "The four genes selected through our process which are dysregulated along with CLDN1 and CLDN7 (PIK3CA, SLC6A6, ASAP1, and TMEM-43) are implicated in a variety of cancers." (PMID 34571860, 2021). "Looking specifically at the mechanisms behind TMEM43’s role in cancer development reveals several different potential areas of further study." (PMID 40725103, 2025). "TMEM43’s role in pathogenicity in cancer is vital, but further research is still needed to provide clinical translation." (PMID 40725103, 2025). "Transmembrane protein 43 (TMEM43) plays a significant role in cancer, with a study revealing its high expression in HCC." (PMID 40607251, 2025). "Taken together, the pathogenesis of these different cancers illustrates the varied mechanistic processes of which TMEM43 can alter cancer pathogenesis." (PMID 40725103, 2025). "Transmembrane protein 43 (TMEM43), a member of the transmembrane protein subfamily, plays a critical role in the initiation and development of cancers." (PMID 35260078, 2022). "However, the function and role of TMEM43 in cancer are vague." (PMID 35260078, 2022). "More recently, the Lin group used a functional genomics approach to identify a transmembrane protein of unknown function, TMEM43 (also referred as LUMA) as a new CARMA3-binding partner that serves as a critical mediator of EGFR-induced NF-κB activation in cancer cells." (PMID 30158935, 2018). "Moreover, TMEM43 was identified to activate the nuclear factor kappa B (NF-kB) pathway through epidermal growth factor receptor (EGFR) signaling or stabilize pre-MRNA processing factor 3 (PRPF3), thus promoting cancer cell proliferation, survival, and migration." (PMID 40725103, 2025).
cardiovascular disease (6 papers, 2015 to 2024). "TMEM43 is involved in cardiovascular disease and plays a major role in metabolic pathways; this gene variant changes the binding of miR-30a and is upregulated in HD, and TMEM43 is downregulated in HD BA9 samples." (PMID 36553652, 2022). "Systems genetics analysis revealed that TMEM43 was involved in cardiac- and metabolism-related pathways, suggesting that TMEM43 is closely associated with cardiovascular disease." (PMID 36230956, 2022). "Ourstudy defined the importance of Tmem43 for cardiac- andmetabolism-related pathways, suggesting that cardiovascular disease-relevantrisk factors may also increase risk of metabolic and neurodegenerative diseasesvia TMEM43-mediated pathways." (PMID 34766515, 2022). "In this study, we used a high-power andhigh-precision systems genetics approach to explore Tmem43 genefunction and identified novel TMEM43-induced mechanisms, pathways, and networksrelevant to heart function and cardiovascular diseases." (PMID 34766515, 2022). "Systems genetics analysis has also defined the importance of transmembrane protein 43 (TMEM43) in cardiac- and metabolic-related pathways, suggesting that cardiovascular disease-relevant risk factors may also increase risk of metabolic and neurodegenerative diseases via TMEM43-mediated pathways." (PMID 38317187, 2024). "However, as a transmembrane protein, TMEM43 may be involved in ferroptosis in cardiovascular disease." (PMID 36230956, 2022).
cardiac disease (5 papers, 2014 to 2024). "Along with the variant spectrum of TMEM43 associated with the heart diseases reported in the human gene mutation database (Top), the arginine at position 372 as well as amino acids in the transmembrane domain (TM) and loop regions of TMEM43 are highly conserved across organisms." (PMID 34050020, 2021). "We further hypothesized that Tmem43 interacts with othercandidate genes involved in pathogenesis of cardiac diseases and we could findthose genes by identifying the genetic correlates of Tmem43 andenriching with similar biological functions, pathways, and phenotypes." (PMID 34766515, 2022).
genetic disorder (1 paper, 2019). "Although mutations in the human EMD gene are most closely tied to the genetic disorder EDMD1, similar phenotypes arise from mutations in genes coding for interacting proteins, such as LMNA, SYNE1, SYNE2, and TMEM43." (PMID 30871242, 2019).
inflammation (1 paper, 2023). Aberrant reaction of the microcirculation characterized by movement of fluid and leukocytes from the blood into extravascular tissues. "TMEM43 Knockdown aggravated cardiac inflammation response; increased serum MDA, cardiac MDA, non-heme iron and ferric iron." (PMID 37942067, 2023).
myopathy (1 paper, 2025). A disease of the muscle in which the muscle fibers do not function properly. "Two heterozygous missense mutations in TMEM43, p.E85K and p.I91V, have been identified in two patients with EDMD-related myopathy." (PMID 40725103, 2025).
TMEM43 also shares sentences with these, for which no sentence is quoted: breast cancer (40 papers); muscular dystrophy (6); breast tumors (5); heart failure (5); triple-negative breast carcinoma (3); cardiac arrhythmias (2); catecholaminergic polymorphic ventricular tachycardia (2); colorectal cancer (2); familial hypercholesterolemia (2); hypertrophic cardiomyopathy (2); long QT syndrome (2); African trypanosomiasis (1); amyotrophic lateral sclerosis (1); Arthritis (1); atherosclerosis (1); breast invasive carcinoma (1); Brugada syndrome (1); Cardio-cutaneous syndromes (1); Charcot-Marie-Tooth disease (1); cholangiocarcinoma (1); conduct disorder (1); Desminopathy (1); diabetic kidney disease (1); injury (1); long QT syndrome 3 (1); Lynch syndrome (1); Marfan syndrome (1); metabolic disease (1); neurodegenerative disease (1); neuropathy (1).
A further 9 diseases each share a sentence with TMEM43 in 1 paper.